ENSG00000273047 (novel transcript, LIME1-SLC2A4RG readthrough)
Gene: Protein-coding gene on chromosome 20 (63,738,270 to 63,740,398, forward strand). Ensembl gene ENSG00000273047.
Genetic constraint (gnomAD): Loss-of-function variants: 4 observed, 4.64 expected, observed/expected ratio (o/e) 0.86, 90% interval 0.42 to 1.75. That is too few expected variants to judge how well the gene tolerates losing a copy. Missense variants: 110 observed, 86.55 expected, observed/expected ratio (o/e) 1.27, 90% interval 1.09 to 1.49. Synonymous variants: 46 observed, 39.06 expected, observed/expected ratio (o/e) 1.18, 90% interval 0.93 to 1.51.